BRAF (B-Raf proto-oncogene, serine/threonine kinase)
Diseases named in the same sentence as BRAF in open-access papers (continued):
Sharing a sentence is not in itself a finding about the gene and the disease.
thyroid cancer (continued). "Additionally, BRAF fusions and RET fusions were found in both cohorts, and activation of epithelial to mesenchymal transition (EMT) was also shown in both transcriptomes, all of which are typical features of thyroid cancer." (PMID 36941725, 2023). "The IMPDH2S280C mutation appeared in a BRAFV600E-mutated patient with a subsequently recurrent thyroid cancer, and the PFKFB4Y366C mutation occurred on a background NRASQ61K mutation, whereas the DICER1D1810H mutation occurred in a patient with no BRAF/RAS mutation." (PMID 34791326, 2022). "In addition to its individual functions, TTYH3 may also promote tumorigenesis by fusion with BRAF serine/threonine kinase (TTYH3-BRAF fusion protein) in glioblastoma, histiocytic sarcoma, and thyroid carcinoma 36-38." (PMID 35844789, 2022). "The limitation of the current study may be that we failed to prove the clinical utility of BRAF, KRAS, NRAS, and TERT promoter mutation as circulating markers in early-staged thyroid cancers distinguishing from benign thyroid lesions or healthy individuals." (PMID 33915745, 2021). "Also, while mutation data was not utilized, the BRAF and RAS mutation classes were well distinguished in THCA (Thyroid carcinoma)." (PMID 34567063, 2021). "All things considered, our results corroborate the hypothesis that BRAF, with its high PPV for thyroid cancer, can be used to “rule-in” malignancy and guide treatment by referring patients with mutation-positive nodules to initial TT as opposed to diagnostic HT." (PMID 32351561, 2020). "Moreover, unlike thyroid cancer, CYP2S1 expression was downregulated in BRAF-mutated colon adenocarcinomas compared to BRAF wild-type ones." (PMID 32913191, 2020). "In thyroid cancer cell lines with wild-type BRAF, WIPF1 expression was robustly upregulated upon introduced expression of BRAF V600E (P=0.03) whereas the opposite was seen upon BRAF knockdown or treatment with BRAF V600E or MEK inhibitors in cells harboring BRAF V600E." (PMID 27863429, 2017). "Our data support the hypothesis that sorafenib may be effective against dedifferentiated thyroid cancers of all histological subtypes and regardless of their BRAF status." (PMID 25879531, 2015). "Furthermore, activated BRAF promotes cell survival by inducing the expression or the phosphorylation of BCL-2 family members and suppresses apoptotic responses against staurosporine and TNFα/cycloheximide in thyroid carcinoma cells." (PMID 26084290, 2015). "Our lab previously demonstrated that the inhibition of oncogenic BRAF results in dramatic tumor reduction in a model of human ATC and several other groups have shown that dasatinib treatment effectively reduces tumor growth in mice implanted with human BRAFV600E-positive thyroid cancer cells." (PMID 24994118, 2014). "The potential effects of BRAFV600E-inhibitors on the immune response have not been investigated in thyroid cancer because all previous studies using human thyroid cancer cells have used immunocompromised mice and novel genetically engineered mice with BRAF tumors rarely show aggressive behavior." (PMID 24994118, 2014). "In order to decrease possible resistance through wild-type BRAF signaling and other pathways, this study supports further investigation of combination targeted therapy including a BRAF600E inhibitor in the treatment of BRAFV600E-positive thyroid cancer patients." (PMID 24673746, 2014). "Similarly, treatment with BRAF inhibitors has been shown to activate protective autophagy via the AMP-activated protein kinase–Unc-51-like autophagy activating kinase 1 axis (AMPK–ULK1 axis), thereby contributing to drug resistance in BRAF-mutant thyroid cancers." (PMID 40843353, 2025). "Although no clinical data is currently available for its use in thyroid cancer, there is an ongoing phase 2 trial examining encorafenib combined with binimetinib, with or without immunotherapy (nivolumab), in patients with metastatic BRAF V600E mutant RR-DTC (NCT04061980)." (PMID 37435488, 2023).
thyroid cancer (continued). "However, vemurafenib is not effective in non-BRAF mutant thyroid cancer cell lines." (PMID 37325052, 2023). "Besides, using transcriptional and mutational landscape, well-differentiated thyroid cancer could be classified as three molecular subtypes including BRAF-like, RAS-like, and Non-BRAF-Non-RAS." (PMID 36494673, 2022). "Interestingly, no occurrences of the BRAF mutation occurred alongside a TERT promoter mutation, suggesting a relative rarity of this mutation in comparison to its frequency in more aggressive thyroid cancers." (PMID 31443155, 2019). "In addition to well-known BRAF, RAS, and RET mutations, NGS technology facilitated detection of new somatic alterations in thyroid cancer such as MITF, MDM2, JAK3, FLI1, IDH1 etc., all in which the significance of thyroid cancer has not been delineated yet." (PMID 27871285, 2016). "The activating point mutation V600E in exon 15 of the BRAF gene was not recognized in the hyperplastic nodule of this case, but the prolonged TSH stimulation might promote malignant transformation and development of thyroid cancer in dyshormonogenic goiter." (PMID 22934199, 2012). "Multi-kinase inhibitors targeting the MAPK pathway, such as Vermurafenib (BRAF) and Selumetinib (MEK) are under study for advanced thyroid cancers, though none of them have yet been approved by the FDA." (PMID 35053446, 2022). "We found that anlotinib inhibits the cell viability of thyroid cancer cells, and arrests cells at the G2/M phase, most likely due to abnormal spindle assembly, but not the BRAF/MEK/ERK pathway, one of the most important signaling pathways in thyroid cancer." (PMID 30139768, 2019). "Recently, genetic and molecular analyses (such as tests for BRAF, RET/PTC, and RAS, among others) revealed diverse molecular characteristics of thyroid cancers, but most clinical trials applying RA did not analyze these factors." (PMID 29085335, 2017). "However, we detected the phosphorylated levels of MEK and ERK in thyroid cancer cells with overexpression or knockdown of IGFBP7 and found that IGFBP7 did not impact on the BRAF-MEK-ERK pathway (data not shown)." (PMID 31183073, 2019). "Recent exploration of the mutational landscape of follicular thyroid cancers (FTCs) has suggested that perhaps well differentiated thyroid cancers could best be classified in three molecular subtypes: BRAF-like, RAS-like and Non-BRAF-Non-RAS." (PMID 30249281, 2018).
lung carcinoma (577 papers, 2009 to 2026). "Currently, the only precision medicine options for RAF-mutated lung cancer are dabrafenib (combined with trametinib) and encorafenib (combined with binimetinib), both of which target the BRAF p.V600 mutation in combination with MEK inhibitors." (PMID 40647542, 2025). "Since lung cancer had the highest absolute number of tumors with BRAF mutations, we focused our subsequent analyses on the clinical characteristics and outcomes of NSCLC patients with BRAF alterations." (PMID 41282105, 2025). "We report the first case of concomitant lung carcinoma and pleural metastasis of papillary thyroid carcinoma with BRAF V600E mutation." (PMID 39950095, 2025). "Nevertheless, in patients with lung cancer, approximately 70% of BRAF mutations are non-V600 mutations, leaving these patients without a targeted therapy." (PMID 40591555, 2025). "In this report, we present a case of inoperable stage IIIA lung adenocarcinoma with a BRAF V600E mutation that underwent radical lung cancer surgery following neoadjuvant targeted therapy." (PMID 41480531, 2025). "We report the first case, to our knowledge, of concomitant lung carcinoma and pleural metastasis of papillary thyroid carcinoma with BRAF V600E mutation." (PMID 39950095, 2025). "Of note, enrichment of the BRAF V600E mutation in cutaneous metastatic disease has also been documented for other types of cancer (lung cancer, papillary thyroid carcinoma), which only rarely affect the skin." (PMID 39935827, 2025). "Herein, we presented 3 cases of NSCLC with BRAF non-V600E mutations and reviewed the current state of therapies for this particular population of lung cancer." (PMID 38601760, 2024). "In our case report, we present the first case of a patient with BRAF V600E-mutated lung cancer, poor PS, acute respiratory failure, and a history of treatment for castration-resistant prostate cancer who was administered dabrafenib and trametinib." (PMID 39759653, 2024). "In Japan, ROS1 fusion gene testing has been covered by insurance since 2017, and BRAF V600E mutation testing since 2018, but they were hardly investigated in lung cancer cases from 2008 to 2014 when our patients were enrolled." (PMID 39539600, 2024). "In a case report, it was reported that an elderly patient with BRAF V600E-mutated lung cancer and poor PS died within a short time after starting treatment." (PMID 39759653, 2024). "In conclusion, this case of poorly differentiated lung carcinoma with the BRAF K601E mutation demonstrates the challenges of treating complex cancer cases." (PMID 39040442, 2024). "Combination therapy strategies have enhanced the treatment efficacy in lung cancer patients harboring the BRAF V600E mutation." (PMID 38474400, 2024). "For this reason, different combination therapies have been proposed for patients carrying mutations in BRAF in EGFRm lung cancer." (PMID 39497713, 2024). "In one patient, the genotype of primary lung cancer puncture was GC, and there was a missense mutation in exon 15 of BRAF gene." (PMID 38764053, 2024). "Within the context of lung cancer, BRAF gene mutations have been identified, particularly among patients diagnosed with NSCLC." (PMID 38754409, 2024). "The V600E activating mutation is the most common variant across tumour types, representing 90% of BRAF mutations, though it accounts for merely 50% of BRAF mutations in lung cancer." (PMID 38347643, 2024). "This case report underscores the complexities and challenges of treating poorly differentiated lung carcinoma with the BRAF K601E mutation, highlighting the nuanced nature of cancer therapies, particularly in cases involving less common mutations." (PMID 39040442, 2024).
lung carcinoma (continued). "In some cases, such as with smokers harboring BRAF-mutant lung cancer, the presence of such a mutation is associated with longer median progression-free survival (PFS) when compared to non-mutant groups when treated with immune checkpoint inhibitors." (PMID 38539548, 2024). "We report a case of limited effectiveness of dabrafenib and trametinib in a 59-year-old man with poorly differentiated lung carcinoma and a rare BRAF K601E mutation." (PMID 39040442, 2024). "Diseases associated with BRAF mutation include melanoma, cardio-faciocutaneous syndrome, lung cancer, and many other malignancies." (PMID 39684934, 2024). "To date, BRAF gene mutations are recognized as one of the genetic factors contributing to the development of various types of cancer, including lung cancer." (PMID 39199653, 2024). "BRAF gene mutations are present in a minority of lung cancer cases, with an estimated prevalence of about 1–3% in NSCLC." (PMID 39199653, 2024). "Dabrafenib plus trametinib has been approved for the treatment of BRAF V600E mutation‐positive advanced non‐small cell lung cancer (NSCLC)." (PMID 38766698, 2024). "Although dabrafenib plus trametinib has been approved for BRAF V600E mutation positive advanced non‐small cell lung cancer (NSCLC), data on its efficacy against uncommon BRAF mutations are still limited due to their rare frequency." (PMID 38766698, 2024). "Two patients with BRAF class 3–mutated metastatic non–small-cell lung cancer (NSCLC) were treated with erlotinib at our Institution after failure of standard therapies." (PMID 39637338, 2024). "Mutated BRAF is identified in 1%–5% non‐small cell lung cancer (NSCLC) patients, with non‐V600 mutations accounting for 50%–70% of these." (PMID 38770647, 2024). "First, an adenovirus that delivered expression of mutationally activated Phosphoinositide 3-Kinase (PI3K) appeared to modulate the activity of BRAF in a murine model of lung cancer with a BRAF activating mutation." (PMID 36678835, 2023). "For instance, PTEN is rarely mutated in KRAS- and BRAF-driven human lung cancers, and yet Pten inactivation provides a very strong tumor fitness advantage in our autochthonous mouse models." (PMID 37828026, 2023). "Combining anti-FAK and MEK therapy would be valuable in lung cancer patients presenting KRAS or BRAF mutations, as these alterations are known to activate the FAK signaling cascade on top of the classical MAPK cascade involving MEK1/2." (PMID 36678835, 2023). "This study aimed to analyze the clinicopathological features of lung carcinomas with BRAF mutations, focusing on V600E vs. non-V600E and the presence of co-mutations." (PMID 37999148, 2023). "Vemurafenib was first developed against lung cancers with the mutated form of the serine/threonine kinase BRAF, BRAFV600E." (PMID 37833251, 2023). "It is reported that BRAF mutation rate in NSCLC is up to 3.5–4%, and BRAF V600E mutation is found to be the mosot frequent BRAF mutation in lung cancer, accounting for roughly 50% of these BRAF-mutant NSCLC cases." (PMID 36759818, 2023). "Lung-ETAC is a rare occurrence in lung cancer, and the coexistence of this histologic subtype with a BRAF p.V600E mutation adds an additional layer of rarity." (PMID 38124787, 2023). "Treatment with vemurafenib has also provided some evidence of activity on brain metastases and meningeal carcinomatosis in BRAF V600E mutated lung cancer, although in retrospective series." (PMID 36230797, 2022). "The technique is useful for studying the incidence and clinicopathological features of BRAF V600E/K mutation in lung cancer patients." (PMID 36553654, 2022). "About 2–4% of patients with lung cancer carry BRAF mutations, predominantly in those with lung adenocarcinoma." (PMID 36543792, 2022). "The upregulation of cyclin-dependent kinase 4 (CDK4) was also reported to mediate acquired resistance to dabrafenib combined trametinib in lung cancer patients with BRAF V600E mutation." (PMID 36508072, 2022).
lung carcinoma (continued). "Further analysis has reported that patients with BRAF-mutated lung cancer have low/intermediate tumor mutational burden (TMB) and microsatellite-stable status." (PMID 36543792, 2022). "Crizotinib was approved to treat advanced NSCLC with rearranged anaplastic lymphoma kinase (ALK) or ROS1 gene, and dabrafenib which targets a rare mutation in lung cancer (BRAF V600E) was approved for the treatment of BRAF-positive advanced NSCLC." (PMID 35061839, 2022). "In a retrospective study of 37 BRAF-mutated lung cancer patients, ORR was 24% and PFS was 3.1 months, which was slightly better than that of patients with EGFR mutation." (PMID 35407463, 2022). "Only one patient had a BRAF G596R mutation, which is more typically seen in lung cancer and is present in 0.02% of all malignant solid tumors." (PMID 35159047, 2022). "In preclinical models of lung cancer, BRAF mutations seem to promote tumourigenesis at an early stage, particularly when other mutations co-occur." (PMID 36230797, 2022). "In this review, we describe changes in the landscape of BRAF-mutated lung cancer treatment and analyze insights from major clinical trials in the context of future therapeutic prospects." (PMID 33474634, 2021). "The BRAF V600 mutation accounts for 50% of all BRAF mutations in advanced-stage lung cancer at diagnosis and acts as an addictive oncogenic driver in LUAD." (PMID 34575554, 2021). "BRAFV600E mutation represents the most frequent BRAF mutation in lung cancer, accounting for approximately 50% of BRAF-mutant NSCLC, whereas fewer mutations have been identified at the G469A and G594G sites." (PMID 33474634, 2021). "In this review, we describe the changes in the landscape of BRAF-mutated lung cancer treatment and provide insights and future perspectives by analyzing major clinical trials." (PMID 33474634, 2021). "Different from the high frequency of EGFR mutation in lung cancer, a high percentage (50%) of BRAF mutation was found in BA." (PMID 34663408, 2021). "Combination of BRAF-specific inhibitor dabrafenib and mitogen-activated protein kinase kinase (MEK) inhibitor trametinib is the standard treatment for BRAF V600E-mutated lung cancer." (PMID 34484797, 2021). "Despite activating BRAF mutations being very prevalent in lung cancer, the impact on response to BRAF inhibitors of changes other than V600 are not well documented and research is necessary." (PMID 33947144, 2021). "The median duration of time elapsed from diagnosis of EGFR-mutant lung cancer to the detection of acquired BRAF mutation was 33.8 months (95% CI: 9.0–99.1 months)." (PMID 34921211, 2021). "In parallel, BRAF mutation was found in lung cancer even though its association with immunotherapy efficacy is controversial." (PMID 34248926, 2021). "BRAF/MEK inhibitors are effective treatment in BRAF-mutated lung cancer even under critical conditions." (PMID 34484797, 2021). "The present findings showed low incidence of BRAF V600E mutation in the studied lung cancer population, and that the newly established RT-qPCR method and BRAF V600E-specific antibody have high concordance in BRAF V600E detection." (PMID 33037234, 2020). "Sixty‐one percent (11/18) of BRAF mutations were found in lung cancers and 16.7% (3/18) in pancreatic cancers." (PMID 32757330, 2020). "BRAF V600E mutation transduces strong growth and survival signals for cancer cells, and is widely present in various types of cancers including lung cancer." (PMID 33037234, 2020). "BRAF mutations occur with a low prevalence of only 2–5% in Caucasian lung cancers, and V600 mutations (amino acid substitution for valine at position 600) accounted for ~50%, with the rest of cases harbor non-V600 mutations." (PMID 32411601, 2020). "V-RAF murine sarcoma viral oncogene homolog B1 (BRAF) mutated non-small-cell lung cancer (NSCLC) is an exceptionally rare form of lung cancer, found only in one to two percent of patients with an NSCLC diagnosis." (PMID 33704186, 2020).